GPX4 (glutathione peroxidase 4)
Diseases named in the same sentence as GPX4 in open-access papers (continued):
Sharing a sentence is not in itself a finding about the gene and the disease.
gastric cancer (continued). "By regulating ferroptosis, GPX4 can prevent the development of gastric cancer and chemical resistance." (PMID 40969276, 2025). "Targeting the regulation of GPX4 has emerged as a promising approach to induce ferroptosis and develop effective therapy for gastric cancer." (PMID 40070026, 2025). "We further investigated the pathological correlation between OTUD5 and GPX4 in human gastric cancer." (PMID 40070026, 2025). "In gastric cancer cells, GPX4 enhances EMT and metastasis by depleting ROS and inhibiting ferroptosis 30, further suggesting an important facilitating role of GPX4 in cellular mesenchymal-like transformation." (PMID 40860189, 2025). "qPCR revealed that GPX4 knockdown in gastric cancer cells led to a corresponding decrease in IDO1 mRNA levels." (PMID 40365295, 2025). "In gastric cancer, it induces ferroptosis by inhibiting GPX4 and GSS, thereby elevating lipid ROS levels; this effect can be significantly reversed by ferroptosis inhibitors." (PMID 40994946, 2025). "OTUD5 depletion destabilizes GPX4, promotes lipid peroxidation and sensitizes gastric cancer cells to ferroptosis." (PMID 40070026, 2025). "In the present study, CIRT significantly increased intracellular iron and ROS levels, upregulated ACSL4 expression, and downregulated GPX4 expression in gastric cancer cells." (PMID 40917841, 2025). "In the MFC cell-derived subcutaneous xenograft model, GPX4-knockdown reduced tumor volume compared to scramble controls (P < 0.001), demonstrating potent suppression of gastric cancer progression." (PMID 40365295, 2025). "These metabolites enhance ROS accumulation by suppressing the expression of SLC7A11 and GPX4 in gastric cancer cells, ultimately inducing ferroptosis." (PMID 38292937, 2024). "LF3 is a 4-thioureido-benzenesulfonamide derivative that profoundly inhibits the interaction between β-catenin and TCF4 and reduces the expression of GPX4, inducing iron-induced death in gastric cancer cells." (PMID 38952556, 2024). "Similar to our results, a previous study reported that OTUB1 interacted with CST1 and enhanced the protein stability of GPX4, thereby reducing the ubiquitination of GPX4, inhibiting ferroptosis, and promoting the metastasis and progression of gastric cancer." (PMID 39500879, 2024). "Apatinib, a tyrosine kinase inhibitor, has been reported to induce ferroptosis in gastric cancer cells by inhibiting GPX4 activity." (PMID 39238647, 2024). "Intriguingly, beta-catenin conferred ferroptosis resistance in gastric cancer by binding to the promoter region of GPX4 and inducing its expression." (PMID 38341410, 2024). "Suppression of CDO1 impedes Erastin-triggered ferroptosis in gastric cancer cells by augmenting intracellular levels of glutathione and the expression of GPX4, thereby abating the generation of reactive oxygen species and lipid peroxidation." (PMID 38370477, 2024). "Mechanistic studies revealed that POLE2 overexpression elevated NRF2 expression and activity and subsequently activated GPX4, which then prevented lipid peroxidation and ferroptosis in human gastric cancer cells." (PMID 38070189, 2024).
gastric cancer (continued). "As expected, the inhibitory effects of ROS generation, lipid peroxidation and PUFAs oxidation in human gastric cancer cells with POLE2 overexpression were also blunted by either NRF2 or GPX4 silence." (PMID 38070189, 2024). "Mechanistic studies revealed that POLE2 overexpression elevated NRF2 expression and activity and subsequently activated GPX4, which then prevented ferroptosis of human gastric cancer cells." (PMID 38070189, 2024). "Collectively, these results imply that POLE2 overexpression inhibits ferroptosis of human gastric cancer cells through activating the NRF2/GPX4 pathway." (PMID 38070189, 2024). "In general, our findings first reveal that POLE2 overexpression inhibits ferroptosis of human gastric cancer cells through activating the NRF2/GPX4 pathway and provide a theoretical principal of molecular therapy for gastric cancer through inhibiting POLE2." (PMID 38070189, 2024). "The β-catenin/TCF4 complex, by promoting the expression of GPX4, confers resistance to ferroptosis in gastric cancer cells." (PMID 39532842, 2024). "The β-catenin/TCF4 transcriptional complex directly binds to the GPX4 promoter region and induces its expression, thereby inhibiting ferroptosis in gastric cancer cells." (PMID 39309441, 2024). "Meanwhile, we conducted western blotting to investigate the correlation between ABCC2 expression and SLC7A11 and GPX4 in gastric cancer cell lines under different nutritional conditions." (PMID 39095325, 2024). "In general, our findings reveal that POLE2 overexpression inhibits ferroptosis of human gastric cancer cells through activating the NRF2/GPX4 pathway and provide a theoretical basis of molecular therapy for gastric cancer through inhibiting POLE2." (PMID 38070189, 2024). "For instance, CST1 regulated GPX4 protein stability to promote gastric cancer metastasis and EMT and inhibit ferroptosis." (PMID 39247595, 2024). "It was reported that Wnt/β-catenin signaling confers ferroptosis resistance by targeting GPX4 in gastric cancer." (PMID 39501138, 2024). "JDA, an extract of Jiyuan Rabdosia rubescens, has also been observed to induce ferroptosis via similar mechanisms by downregulating GPX4 expression in gastric cancer cells." (PMID 38292937, 2024). "Gastric cancer tissues showed more positive staining with GPX4, NRF2, and SLC7A11 when compared with adjacent non-tumor tissues; GPX4 and NRF2 staining was mainly seen in the nucleoplasm or cytoplasm, while SLC7A11 staining patterns were mainly cytoplasmic." (PMID 37768308, 2023). "Glutathione peroxidase 4 and nuclear factor erythroid 2-related factor 2 expressions were higher in all 6 gastric cancer cell lines compared to normal gastric epithelial cells." (PMID 37768308, 2023). "It is a key experiment to explore the regulation of GPX4 stabilization by CST1 by mutating the ubiquitination site of GPX4 and promoting gastric cancer migration and invasion." (PMID 36369321, 2023). "Based on this result, we found that knockdown of GPX4 combined with PD-L1 inhibitor therapy can improve immunotherapy efficacy in gastric cancer, suggesting a new therapeutic strategy for this disease." (PMID 37649598, 2023). "It was lately reported that the Wnt/β-catenin axis suppressed ferroptosis in gastric cancer cells via targeting GPX4." (PMID 37671945, 2023). "GPX4 expression was downregulated in MCF cells (mouse gastric cancer cells) to explore its effect on the gastric cancer microenvironment." (PMID 37649598, 2023). "Forty-two gastric cancer samples and paracancerous samples were included, and all cases were detected with glutathione peroxidase 4, nuclear factor erythroid 2-related factor 2, and solute carrier family 7 member 11 by immunohistochemistry." (PMID 37768308, 2023). "Our research shows that CST1 reduces intracellular ROS by stabilizing GPX4 protein, thereby maintaining the ROS homeostasis of gastric cancer cells in the EMT state, inhibiting ferroptosis and, in turn, promoting the metastasis of gastric cancer." (PMID 36369321, 2023).
gastric cancer (continued). "GPX4 was lower in gastric cancer compared with other cancers, so gastric cancer cells were more prone to ferroptosis than other cells." (PMID 37781038, 2023). "Apatinib inhibited the transcription of GPX4 by regulating the srebp1a-mediated pathway and culminating in lipid peroxidation-induced ferroptosis in gastric cancer." (PMID 35785165, 2022). "Another study showed that silencing SIRT6 induced ferroptosis in gastric cancer cells by inducing inactivation of Keap1-Nrf2 and low expression of GPX4, thereby improving the sensitivity of gastric cancer cells to sorafenib." (PMID 36038533, 2022). "Depletion of SIRT6 inactivates the Keap1-NRF2 pathway and downregulates GPX4 expression, and enhances the sensitivity of gastric cancer cells to sorafenib-induced ferroptosis." (PMID 34796174, 2021). "Apatinib, an approved anti-angiogenic agent for advanced gastric cancer therapy, can induce lipid peroxidation by inhibiting the expression of GPX4 in gastric cancer cells, and thus leading to ferroptosis." (PMID 34796174, 2021). "GPX4 is up-regulated in colon and liver cancer whereas down-regulated in the pancreas, breast, kidney, and gastric cancer." (PMID 32596160, 2020). "High expression of the anti-ferroptotic enzyme GPX4 has been linked to poor survival outcomes, while the SLC7A11 transporter may be crucial in the development of platinum resistance in gastric cancer." (PMID 40846695, 2025). "Additionally, OTUD5 silencing and nutlin‐3a‐induced GPX4 degradation enhances the sensitivity of gastric cancer cells to ferroptosis in vivo." (PMID 40070026, 2025). "Furthermore, upregulation of ATF3 can downregulate the transcription of GPX4, promote ferroptosis, and inhibit the proliferation of gastric cancer cells, providing a potential therapeutic target for gastric cancer." (PMID 41550926, 2025). "This article further proposes the potential of ferroptosis biomarkers (such as 4-HNE and GPX4) in early diagnosis and prognosis assessment of gastric cancer and emphasizes the need for precision medicine to optimize ferroptosis-targeted strategies, balancing efficacy and safety." (PMID 40861444, 2025). "However, the effect of GPX4 expression on the immune microenvironment of gastric cancer was still unclear." (PMID 40365295, 2025). "This suggests that artesunate may exert its cytotoxic effects by disrupting the delicate balance between intracellular iron levels and antioxidant defense systems, including GPX4, thereby promoting ferroptosis in gastric cancer cells." (PMID 40946428, 2025). "The identification of an inhibitor for OTUD5 could potentially lead to the suppression of GPX4, preventing the onset and progression of gastric cancer." (PMID 40070026, 2025). "Targeting the degradation pathways of GPX4 to induce ferroptosis of gastric cancer cells may present a promising therapeutic approach." (PMID 40070026, 2025). "CST1 promotes gastric cancer metastasis by regulating GPX4 protein stability via OTUB1." (PMID 39605891, 2024).
gastric cancer (continued). "POLE2 overexpression inhibits ferroptosis in human gastric cancer cells through activating NRF2/GPX4 pathway, and inhibiting POLE2 may be a crucial strategy to treat gastric cancer." (PMID 38070189, 2024). "Liu has identified that CA, DCA, and CDCA significantly activate the FXR receptor, resulting in the increased expression of BTB and CNC homology 1 (BACH1), glutathione (GSH) synthetase, and GPX4 in gastric cancer cells of HGC-27 and MKN-45 in a ferroptosis-dependent manner." (PMID 39769418, 2024). "We thus determined whether the NRF2/GPX4 pathway was essential for POLE2 overexpression‐mediated inhibition on ferroptosis in gastric cancer." (PMID 38070189, 2024). "We utilized Kaplan–Meier survival curves to examine the correlation of overall survival with GPX4 expression in 178 gastric cancer (GC) patients in our study and the findings revealed a significant reduction in overall survival in GC patients with high GPX4 expression." (PMID 38369484, 2024). "In addition, inhibition of GPX4 can induce ferroptosis in DDP-resistant gastric cancer cells and attenuate DDP-resistance of gastric cancer." (PMID 39039611, 2024). "More importantly, overexpression of NRF2 could obviously rescue TFP-induced downregulation of GPX4 and xCT in gastric cancer cells." (PMID 38244583, 2024). "Additionally, the Wnt/β-catenin signaling pathway in gastric cancer cells reinforces resistance to iron death by targeting GPX4." (PMID 38370477, 2024). "CST1 stabilizes GPX4, inhibiting ferroptosis and promoting gastric cancer metastasis." (PMID 39588389, 2024). "Indeed, previous reports have shown that GPX4 expression is an independent poor prognostic factor in gastric cancer, acute lymphoblastic leukemia, and malignant lymphoma." (PMID 39594843, 2024). "Glutathione peroxidase 4 and nuclear factor erythroid 2-related factor 2 expressions were significantly higher in gastric cancer, which may be potential biomarkers of gastric cancer." (PMID 37768308, 2023). "Interestingly, Wnt/β-catenin activation due to overexpression of Wnt receptor FZD10 was associated with levantinib resistance; also, Wnt/β-catenin activation induced GPX4 expression and ferroptosis resistance in gastric cancer." (PMID 38036507, 2023). "Consistent with this, TCF was proposed as the transcription factor of GPX4 in gastric cancers." (PMID 37671945, 2023). "In this study, we identified a novel GPx4 inhibitor, PB, which shows good antitumor efficacy without causing significant host toxicity via inducing ferroptosis in both gastric cancer cells and mouse models." (PMID 36923926, 2023). "Inhibition of the MIF signaling pathway in the TME and GPX4 expression in tumor cells may be an important strategy for cold tumor synergistic immunotherapy for gastric cancer." (PMID 37649598, 2023). "We hypothesized that CST1 could regulate gastric cancer progression by regulating GPX4 and ferroptosis." (PMID 36369321, 2023). "We found that gastric cancer tumors with a low HDS may be sensitive to GPX4 inhibitors (ML210, ML162, and 1S3R-RSL-3), survivin inhibitors (YM-155), and dasatinib." (PMID 37649598, 2023). "It has been confirmed that apatinib could inhibit proliferation of gastric cancer cells by inducing glutathione peroxidase 4- (GPX4-) mediated ferroptosis." (PMID 35602105, 2022). "In addition, the statistical results of the survival curve indicated that the survival period of patients with gastric cancer with high expression levels of TET1 or GPX4 was significantly lower than that in patients with low expression of these genes." (PMID 36237989, 2022).
gastric cancer (continued). "The inhibition of Sirtuins 6 (SIRT6), a member of the Sirtuin family of NAD (+)-dependent enzymes, lead to the inactivation of the Keap1/Nrf2 signalling pathway and downregulation of GPX4, which overcomes sorafenib resistance by promoting ferroptosis in gastric cancer." (PMID 36105219, 2022). "Therefore, the clinical data analysis showed that the high expression of TET1 or GPX4 correlated positively with an adverse prognosis in gastric cancer." (PMID 36237989, 2022). "Indeed, inhibition of D5D diminishes the glutathione peroxidase 4 (GPX4) inhibitor RSL3-induced ferroptosis in YCC-16 gastric cancer cells." (PMID 34438249, 2021). "GPX4-MPND fusion gene is a novel molecular event identified in gastric cancer." (PMID 26330360, 2015). "Within the scope of this study, we identified that GPX4, a principal negative regulator of ferroptosis, is markedly overexpressed in gastric cancer patient tissues when compared to normal tissues, suggesting a critical role for GPX4 in enabling gastric cancer cells to evade ferroptosis." (PMID 40070026, 2025). "However, the role of GPX4 in gastric cancer (GC) is unclear." (PMID 40365295, 2025). "Therefore, this study revealed that Atranorin@SPIONs induced ferroptosis of GCSCs by weakening the expression of the Xc-/GPX4 axis and the 5-hydroxymethylcytidine modification of mRNAs in the pathway, thereby achieving their therapeutic effect on gastric cancer." (PMID 36237989, 2022). "In gastric cancer, quercetin induces ferroptosis in gastric cancer cells by targeting SLC1A5 and regulating the p-Camk2/p-DRP1 and NRF2/GPX4 axis." (PMID 40994946, 2025). "Given the critical role of GPX4 in the process of ferroptosis, we extended our investigation to the impact of OTUD5 on ferroptosis in gastric cancer cells." (PMID 40070026, 2025). "For instance, USP7 has been shown to suppress ferroptosis by activating stearoyl-CoA desaturase in gastric cancer, whereas USP8 knockdown enhanced ferroptosis through inhibiting GPX4 in CRC." (PMID 40962058, 2025). "The clinical anesthetic propofol exerts dual regulation on GPX4 and SLC7A11 expression via the miR‐125b‐5p/STAT3 axis, exhibiting proferroptotic effects in gastric cancer models while demonstrating Fe homeostasis protection in neuroblastoma." (PMID 40919133, 2025). "In this study, we utilized metabolomics to reveal that knocking down GPX4 in GC cells reduces M2 macrophage polarization within the TME by regulating kynurenine levels, thereby inhibiting gastric cancer growth." (PMID 40365295, 2025). "In gastric cancer, The β-catenin/TCF4 transcriptional complex induces GPX4 expression, thereby inhibiting ferroptosis." (PMID 41213915, 2025). "Dysregulation of GPX4 expression can lead to resistance to multiple therapeutic strategies, such as etoposide in NSCLC, 5‐fluorouracil (5‐FU) in gastric cancer, tamoxifen in breast cancer and TKIs in leukemia." (PMID 40919131, 2025). "This suppression leads to a decrease of OTUD5 mRNA levels, a consequent reduction of GPX4 protein levels, and an increase of LPO accumulation, ultimately resulting in ferroptosis of tumour cells and the inhibition of gastric cancer progression." (PMID 40070026, 2025). "Glutathione peroxidase 4 (GPX4), a key negative regulator of ferroptosis, is highly expressed in gastric cancer and contributes to tumor growth." (PMID 40070026, 2025). "Oxaliplatin inhibited DNA synthesis to induce apoptosis in gastric cancer cells, while Fe3+ was reduced to Fe2+, depleted GSH, inhibited glutathione peroxidase 4 (GPX4) activity, and induced ferroptosis (manifested by elevated lipid peroxides (LPO) and ROS)." (PMID 40573997, 2025).